TTLL12 (tubulin tyrosine ligase like 12)
Description:
Negatively regulates post-translational modifications of tubulin, including detyrosination of the C-terminus and polyglutamylation of glutamate residues. Also, indirectly promotes histone H4 trimethylation at 'Lys-20' (H4K20me3). Probably by controlling tubulin and/or histone H4 post-translational modifications, plays a role in mitosis and in maintaining chromosome number stability. During RNA virus-mediated infection, acts as a negative regulator of the RIG-I pathway by preventing MAVS binding to TBK1 and IKBKE.
Synonyms: KIAA0153; dJ526I14.2
Tractability: Antibody: its Gene Ontology location is reachable by antibodies, with high confidence. PROTAC: ubiquitination databases record sites on it; its protein half-life has been measured.
Gene: Protein-coding gene on chromosome 22 (43,166,622 to 43,187,134, reverse strand). Ensembl gene ENSG00000100304.
Subcellular location: Cytoplasm; Midbody; Cytoplasm, cytoskeleton, microtubule organizing center, centrosome; Cytoplasm, cytoskeleton, spindle; Nucleus
Subcellular location (Human Protein Atlas): Cytosol; Nucleoplasm; Plasma membrane
Pathways (Reactome):
Metabolism of proteins: Carboxyterminal post-translational modifications of tubulin
Gene Ontology:
Molecular function: histone H4K20 trimethyltransferase activity; histone H4K20me2 reader activity; protein binding; tubulin-tyrosine ligase activity
Biological process: negative regulation of type I interferon-mediated signaling pathway; regulation of mitotic cell cycle; chromatin organization
Cellular component: cytoplasm; cytosol; nucleoplasm; nucleus; centrosome; midbody; spindle
Genetic constraint (gnomAD): Loss-of-function variants: 77 observed, 72.43 expected, observed/expected ratio (o/e) 1.06, 90% interval 0.88 to 1.28. The synonymous counts are far from expectation, so gnomAD's model fits this gene poorly and the ratio says little. Missense variants: 969 observed, 841.69 expected, observed/expected ratio (o/e) 1.15, 90% interval 1.09 to 1.21. Synonymous variants: 437 observed, 356.37 expected, observed/expected ratio (o/e) 1.23, 90% interval 1.13 to 1.33.
Homologues: Orthologues: chimpanzee TTLL12 (99% identical), macaque TTLL12 (98% identical), dog TTLL12 (87% identical), mouse Ttll12 (85% identical), rat Ttll12 (85% identical), guinea pig TTLL12 (84% identical), pig TTLL12 (79% identical), tropical clawed frog ttll12 (65% identical), zebrafish ttll12 (61% identical), Drosophila melanogaster TTLL12 (40% identical), Caenorhabditis elegans ttll-12 (36% identical). Paralogues in human: TTLL8 (15% identical), TTLL4 (14% identical), TTLL6 (14% identical), TTLL13 (14% identical), TTLL7 (13% identical), TTLL3 (13% identical), TTLL11 (13% identical), TTLL2 (12% identical), TTLL10 (12% identical), TTLL1 (11% identical), TTLL9 (11% identical), KPRP (7% identical).
Diseases named in the same sentence as TTLL12 in open-access papers:
TTLL12 is named in the same sentence as 10 diseases in open-access papers, as found by Europe PMC text mining. Sharing a sentence is not in itself a finding about the gene and the disease. The quoted sentences say what the papers report.
prostate carcinoma (2 papers, 2015 to 2022). A carcinoma that arises from epithelial cells of the prostate gland. "Increased TTLL12 (an elongating polyglutamylase) has already been associated with metastatic progression of prostate cancer." (PMID 26460824, 2015). "TTLL12, a serum autoantibody, was overexpressed in prostate cancer patients and regulate cytoskeleton, tubulin modification, and chromosome number stability in prostate cancer." (PMID 35075375, 2022). "We constructed ceRNA networks in the prostate cancer microenvironment and identified lncRNA LINC01082, miRNA hsa-miR-133a-3p, and genes TTLL12, PTGDS, GAS6, CYP27A1, PKP3, and ZG16B as the potential biomarkers to predict prognosis for prostate cancer." (PMID 35075375, 2022). "The most interesting 8 prognostic biomarkers for prostate cancer included lncRNA LINC01082, miRNA hsa-miR-133a-3p, and genes TTLL12, PTGDS, GAS6, CYP27A1, PKP3, and ZG16B." (PMID 35075375, 2022). "lncRNA LINC01082, miRNA hsa-miR-133a-3p, and genes TTLL12, PTGDS, GAS6, CYP27A1, PKP3, and ZG16B are the top RNAs having the potential to predict prognosis for prostate cancer." (PMID 35075375, 2022). "Finally, survival analysis, biological function analysis, and literature researched identified 8 key biomarkers (lncRNA LINC01082, miRNA hsa-miR-133a-3p, mRNA TTLL12, PTGDS, GAS6, CYP27A1, PKP3, and ZG16B) to predict prostate cancer prognosis." (PMID 35075375, 2022).
lung diseases (1 paper, 2021). "Further verification was done by qPCR as we tested five differential peak-related genes (Rras2, Ttll12, Ccr3, Ccr6 and Trps1) with known contributions to lung diseases." (PMID 33902609, 2021).
ovarian carcinoma (1 paper, 2020). A malignant neoplasm originating from the surface ovarian epithelium. "Comparison of the MyoMed-946 and MyoMed-205 proteome data sets suggests that MyoMed-946-treated EDL may contain higher levels of Ttll12 (tubulin-tyrosine ligase-like protein 12) and Tbc1d17, both regulators of tubulin dynamics, correlating in ovarian cancers with a poor outcome." (PMID 33050629, 2020).
viral infection (1 paper, 2024). "Tubulin tyrosine ligase 12 (TTLL12) is a promising target for therapeutic intervention since it has been implicated in tumour progression, the innate immune response to viral infection, ciliogenesis and abnormal cell division." (PMID 38394155, 2024). "TTLL12 is also implicated in the innate immune response to viral infection." (PMID 38394155, 2024).
tumor (5 papers, 2020 to 2025). "Nitrotyrosine (reviews:) and TTLL12 levels increase with tumour progression, suggesting that they are linked." (PMID 38394155, 2024). "This gene can be used as a biomarker to identify diffuse GC early, as we have identified increased levels of TTLL12 in tumor samples from patients predisposed to metastatic progression." (PMID 33351778, 2020). "We originally selected TTLL12 as a potential target for drug development from our multi-omic dissection of human tumours and bioinformatic predictions of enzymatic activity." (PMID 38394155, 2024). "We report a proof of principle that molecules that relieve a potential tumour promoting activity of TTLL12 can be identified, as a step towards developing TTLL12 targeted therapeutic agents." (PMID 38394155, 2024). "TTLL12 may contribute to tumour progression through effects on chromosomal ploidy, mitotic duration and microtubule dynamics." (PMID 38394155, 2024). "An intriguing possibility is that TTLL12 could act as a tumour suppressor through suppression of nitrotyrosine ligation to the C-terminus of detyrosinated α-tubulin and the consequent cell toxicity." (PMID 38394155, 2024). "TTLL12 expression was significantly high in the following variables: men under 50 years old, predominantly in tumor tissues located in the cardia, who evolved to a diffuse histological GC, with the early and non-invasive stage (T1/T2), lymph nodes negative (N0) and absence of distant metastases." (PMID 33351778, 2020). "Possibly, MyoMed-946, in contrast to MyoMed-205, rapidly affects dividing tumor cells via Ttll12 and Tbc1d17, a hypothesis that has to be validated in future studies." (PMID 33050629, 2020). "We identified increased levels of TTLL12, CDC16 and UBE2T in tumor samples from 103 patients with diffuse GC (M1) (p <0.001 for all analyzes)." (PMID 33351778, 2020). "In this work, qPCR and western blot results revealed a significant increase in expression levels of TTLL12, MZT2B, CDC16 and UBE2T in GC tumor samples of diffuse and intestinal-type, when compared with normal gastric tissues." (PMID 33351778, 2020). "Interestingly, in patients with gastrointestinal tumors, it has been found that the expression of genes, such as TLRs, WFDC2, TTLL12, THRA, and EPHB3, which can trigger an immune response and release of pro-inflammatory factors and thus accelerate tumor cell invasion, is disturbed." (PMID 38243957, 2025).
cancer (4 papers, 2015 to 2024). A tumor composed of atypical neoplastic, often pleomorphic cells that invade other tissues. "TTLL12 expression and alterations have been linked to prognosis of various cancers, including prostate, stomach, lung adenocarcinoma, ulcerative colitis, ovarian cancer, and keloids in Chinese patients." (PMID 38394155, 2024). "TTLL12 is a particularly interesting candidate susceptibility gene as its expression has been shown to increase during cancer progression and metastasis." (PMID 26025378, 2015). "We found that TTLL12 is expressed in the proliferating layer of benign prostate and its expression increases during cancer progression." (PMID 38394155, 2024). "The molecules from the screen will be useful for the study of TTLL12, as well as leads for the development of drugs to treat cancer and other pathologies that involve nitrotyrosination." (PMID 38394155, 2024). "This is an important step towards developing molecules that could be used to probe the functions of TTLL12 and ultimately treat cancer and other pathologies by targeting novel pathways." (PMID 38394155, 2024). "This overexpression in cancer could generate serum autoantibodies that recognise TTLL12 specifically in prostate cancer patients." (PMID 38394155, 2024). "TTLL12 is reported to be abnormal in many cancer cells, but its function in GC is still unknown." (PMID 33351778, 2020).
Muscular Disorders (1 paper, 2022). "From twenty genes of “Cellular Development, Cellular Movement, Skeletal and Muscular Disorders”, six DEGs in the top network related to RSK1 KO (TTLL12, ADMA22, FN1, LPAR1, MMP16, and NRN1) were highly correlated with RSK1 expression, with significant R and p values." (PMID 36684450, 2022).
TTLL12 also shares sentences with these, for which no sentence is quoted: gastric cancer (1 paper); gastrointestinal tumors (1); pancreatic cancer (1).